HNF1B (HNF1 homeobox B)
Diseases named in the same sentence as HNF1B in open-access papers (continued):
Sharing a sentence is not in itself a finding about the gene and the disease.
cervical carcinoma (6 papers, 2006 to 2025). A carcinoma arising from either the exocervical squamous epithelium or the endocervical glandular epithelium. "Based on our results, expression of HNF-1β is mostly restricted to adenocarcinomas and can be used as an auxiliary adenocarcinoma marker in the differential diagnosis of poorly differentiated cervical carcinomas." (PMID 25884453, 2015). "In cervical carcinoma, expression of HNF-1β is mostly restricted to adenocarcinomas and can be used as an auxiliary adenocarcinoma marker in the differential diagnosis of poorly differentiated cervical carcinomas." (PMID 25884453, 2015). "Regarding cervical carcinoma, HNF-1β expression has been mentioned exceptionally in mesonephric and some other types of adenocarcinoma." (PMID 25884453, 2015). "We analyzed HNF-1β expression in 155 cervical carcinomas (including 56 adenocarcinomas, 85 squamous cell carcinomas and 14 undifferentiated carcinomas)." (PMID 25884453, 2015). "In cervical carcinoma, expression of HNF-1β has been mentioned in mesonephric and other types of adenocarcinoma." (PMID 25884453, 2015). "Recently, it has been reported that the expression of HNF-1β in cervical carcinoma is mostly restricted to adenocarcinomas and can be used as an auxiliary adenocarcinoma marker in the differential diagnosis of poorly differentiated cervical carcinomas." (PMID 31810492, 2019). "Expression of HNF-1β in carcinoma of the uterine cervix has been mentioned only in two studies." (PMID 25884453, 2015). "To evaluate the relationship between HNF1B and the protein-level expression of clotting factor genes, we performed IHC on 14 gynecologic cancers with cytoplasmic clearing (10 ovarian, 3 endometrial and 1 cervical carcinoma), using an antibody specific to prothrombin." (PMID 24040285, 2013). "However, a systematic analysis of HNF-1β expression in cervical carcinoma has not been performed to date." (PMID 25884453, 2015). "However, a systematic analysis of HNF-1β expression in cervical carcinomas has not been performed to date." (PMID 25884453, 2015).
cholangiocarcinoma (6 papers, 2015 to 2025). A carcinoma that arises from the intrahepatic biliary tree (intrahepatic cholangiocarcinoma) or from the junction, or adjacent to the junction, of the right and left hepatic ducts (hilar cholangiocarcinoma). "HNF-1B was expressed in 107 of 127 (84.3%) of PDACs, 13 of 15 (86.7%) of cholangiocarcinomas, 13 of 18 (72%) of ampullary carcinomas, and 13 of 14 (92.9%) of gallbladder adenocarcinomas." (PMID 30065837, 2018). "In our previous study, we found that cholangiocarcinoma-like HCC (CLHCC), a novel HCC subtype that highly expresses HNF-1β and expresses cholangiocarcinoma-like traits and stem cell-like expression traits, tended to show poorer surgical outcome." (PMID 28684878, 2017).
clear cell renal cell carcinoma (6 papers, 2015 to 2025). "In the subset of clear cell renal cell carcinoma (ccRCC), decreased HNF1B expression was associated with a higher tumour grade and higher T stage." (PMID 33051485, 2020). "It has been shown that down-regulation of HNF-1β in clear-cell renal cell carcinoma is associated with tumor progression and poor prognosis." (PMID 25884453, 2015). "HNF1B hypomethylation has recently been detected in additional clear cell histologies, including endometrial, cervical and renal clear cell cancers, suggesting HNF1B expression and promoter hypomethylation to be a general biomarker of cytoplasmic clearing." (PMID 25378557, 2015). "Among non-pancreaticobiliary carcinomas, clear cell carcinomas of the kidney showed predominantly nuclear HNF-1B expression, while Müllerian origin, including ovarian and endometrial clear cell carcinoma showed nuclear and/or cytoplasmic HNF-1B expression." (PMID 30065837, 2018).
Gitelman syndrome (6 papers, 2015 to 2025). Gitelman syndrome (GS), also referred to as familial hypokalemia-hypomagnesemia, is characterized by hypokalemic metabolic alkalosis in combination with significant hypomagnesemia and low urinary calcium excretion. "Next, we show that HNF1B mutations are not only associated with hypomagnesemia, but with a trend for a more complex pattern of electrolyte abnormalities comparable to Gitelman syndrome." (PMID 31517149, 2019). "Of note, renin-angiotensin-aldosterone system (RAAS) activation is scarce in patients with HNF1β defects, whereas it is one of the main symptoms of Gitelman syndrome." (PMID 35894287, 2022). "The abnormal tubular electrolyte handling associated with HNF1B mutations develops with age and is not restricted to magnesium, but consistent with a more generalized dysfunction of the distal convoluted tubule, reminiscent of Gitelman syndrome." (PMID 31517149, 2019). "In addition, abnormal tubular electrolyte handling associated with HNF1B mutations was not restricted to magnesium and potassium, but was rather consistent with a more generalized dysfunction of the distal convoluted tubule indicative of the Gitelman syndrome." (PMID 32708349, 2020).
MRKH syndrome (6 papers, 2006 to 2024). "The most reported genes implicated in the pathogenesis of MRKH syndrome have been WNT4, LHX1 (LIM homebox protein 1) and HNF1B (hepatocyte nuclear factor-1B)." (PMID 38841305, 2024). "In cases of MRKH syndrome, recurrent microdeletions and microduplications (1q21,1; 2q12.1q14.1; 16p11.2; 17p14.3; 17q12; 22q11.21; 22q11.21q11.23) and mutations in genes located on these loci (RBM8A, PAX8, TBX1, TBX6, LHX, HNF1B, WNT4) have been identified." (PMID 33883018, 2021). "However, absence of phenotype/genotype correlation in addition to non-MRKH uterine malformations is not consistent with a straight relationship between MRKH syndrome and HNF-1β gene defects." (PMID 16441882, 2006).
prostate adenocarcinoma (6 papers, 2010 to 2022). "HNF1B was associated with other genes that could be detected in bladder urothelial carcinoma, liver hepatocellular carcinoma, lung squamous cell carcinoma, uterine corpus endometrial carcinoma, esophageal carcinoma and stomach adenocarcinoma, lung adenocarcinoma and prostate adenocarcinoma." (PMID 33173410, 2020). "Gastroesophageal, lung, and prostate adenocarcinomas occasionally expressed HNF-1B in up to 37% cases." (PMID 30065837, 2018).
thyroid cancer (6 papers, 2010 to 2025). "The expression of PAX8 and HNF1B across normal tissues also supported their tissue specificity, and the extremely high expression of PAX8 in the thyroid could indicate its potential dependency role in thyroid cancer." (PMID 33850477, 2021).
autism (5 papers, 2014 to 2023). Persistent deficits in social interaction and communication and interaction as well as a markedly restricted repertoire of activity and interest as well as repetitive patterns of behavior. "In this French cohort, only 1 of 26 patients with an HNF1B whole-gene deletion were diagnosed with autism as compared to 0 of 13 in the mutation group." (PMID 27234567, 2016). "Interestingly, neurodevelopmental abnormalities, such as autism and developmental delays, have been reported to be associated with HNF1B mutations, but these complications appear to be restricted to patients with the 17q12 deletion." (PMID 32708349, 2020). "Interestingly, several publications show that gene deletion in the 17q12 region (which includes HNF1β) results in the clinical combination of autism/schizophrenia and CAKUT." (PMID 28398236, 2017).
colon carcinoma (5 papers, 2009 to 2022). "Additional experimental validation confirmed that siHNF1B efficacy is correlated with HNF1B mRNA expression levels in diverse colon cancer cell lines." (PMID 33114107, 2020). "We experimentally tested the siRNA efficacy for HNF1B in nine colon cancer cell lines and observed that the correlations between mRNA expression and siRNA efficacy for the HNF1B gene were similar." (PMID 33114107, 2020). "Moreover, relatively high co-expression scores were also observed for RUNX2/ETS1, RUNX2/FOXO3, HNF1B/HNF4A, and HNF1B/FOXA3, suggesting that the DETFs associated with DARs might work together and be responsible for 5-FU resistance in colon cancer cells." (PMID 35252200, 2022). "As shown by the shRNA and sgRNA analyses, HNF1B mRNA expression was significantly correlated with shRNA (PCC; r = 0.66) and sgRNA (PCC; r = 0.69) efficacy in colon cancer cell lines." (PMID 33114107, 2020).
cyst (5 papers, 2015 to 2024). A sac-like closed membranous structure that may be empty or contain fluid or amorphous material. "HNF1b mutations in humans are linked to cyst formation and are associated with severe congenital abnormalities of the kidney, which suggests that HNF1b plays an early role in nephrogenesis." (PMID 26024215, 2015). "Wnt/beta-catenin signaling pathway is suspected to be responsible for cyst growth in HNF1B-MODY." (PMID 35179657, 2022). "Further studies are required, especially in vivo, to explain the role of LPA in HNF1B-MODY pathogenesis and the crucial question to be answered is whether the inhibition of LPA can affect cyst growth in the patients with mutated HNF1B." (PMID 35179657, 2022). "However, it remains unknown whether the interplay between high LPA, low HNF1B and Wnt/β-catenin pathway is a culprit of cyst formation in HNF1B-MODY syndrome." (PMID 35179657, 2022).
developmental delay (5 papers, 2020 to 2025). "In patients with a 17q12 microdeletion, cases of learning disorder, ASD, global developmental delay and motor disorder were observed, in patients with a mutation of HNF1B, a case of learning disorder was observed." (PMID 36969268, 2023). "It has been reported that the gene HNF1B is associated with a variable clinical presentation that includes developmental delay, behavioral problems, microcephaly, epilepsy, brain abnormalities, urinary malformation, and other abnormalities." (PMID 34285689, 2021). "The patient with HNF1B-MODY in our cohort exhibited a syndromic form of the disease characterized by global developmental delay, intellectual disability, epilepsy, dysmorphic features, persistent hypomagnesemia, mildly elevated liver enzymes, and a bicornuate uterus." (PMID 41367630, 2025).
dyslipidemia (5 papers, 2013 to 2026). "Clinically, HNF-1α (MODY3) and HNF-1β (MODY5) mutations are closely associated with dyslipidemia, proteinuria, and CKD progression, with lipotoxicity serving as a key pathogenic driver." (PMID 41291157, 2025). "In fact, dyslipidemia frequently accompanies the mutations and the complete deletion of HNF1B." (PMID 39504571, 2025).
glioma (5 papers, 2017 to 2021). A benign or malignant brain and spinal cord tumor that arises from glial cells (astrocytes, oligodendrocytes, ependymal cells). "IHC results showed that both HNF1B protein expression was upregulated in glioma tissues and positively associated with advanced TNM stage, which was further confirmed by TCGA database." (PMID 34475987, 2021). "Herein, the purpose of the present study was to investigate the explicit role of lncRNA-PVT1 in the pathogenesis of glioma as well as the potential mechanism of lncRNA-PVT1/ miR-1207-3p/HNF1B axis in glioma." (PMID 34475987, 2021). "Western blot results showed that overexpression of miR-1207-3p significantly down-regulated HNF1B compared with the control group, suggesting that HNF1B expression is inversely regulated by miR-1207-3p in glioma." (PMID 34475987, 2021). "In summary, our study identified the interaction between lncRNA-PVT1, miR-1207-3p and HNF1B in glioma." (PMID 34475987, 2021). "The present study further confirmed that transcriptional activation of lncRNA-PVT1 contributed to oncogenesis, whereas knockdown of lncRNA-PVT1 impaired oncogenic function of HNF1B in glioma cells." (PMID 34475987, 2021). "Proliferation of glioma cells in the miR-217+HNF1β (non-3′UTR) group was significantly restored than that in the miR-217+HNF1β group." (PMID 28219405, 2017). "HNF1β was located to the nucleus and was positively correlated with the progression of glioma pathological grades." (PMID 28219405, 2017). "In the present study, we investigated the expression and functions of circ-TTBK2, miR-217, HNF1β, and Derlin-1 in glioma tissues and cells." (PMID 28219405, 2017). "HNF1β was upregulated in glioma tissues and cells and promoted cell proliferation, migration, and invasion, while inhibited apoptosis of glioma cells." (PMID 28219405, 2017). "Immunohistochemical and western blot were used to determine the expression of HNF1β and Derlin-1 in glioma tissues and cells." (PMID 28219405, 2017). "Having confirmed that HNF1β was upregulated in glioma tissues and cells, effects of HNF1β overexpression or downregulation on glioma cells were investigated." (PMID 28219405, 2017). "And the lncRNA-PVT1/miR-1207-3p/HNF1B/MAPK axis might provide a new potential therapeutic target for treatment of glioma." (PMID 34475987, 2021). "In our study, by bioinformatic prediction and experimental verification, we showed that HNF1B could act as a direct target of miR-1207-3p in glioma." (PMID 34475987, 2021). "Thus, our data suggested that lncRNA-PVT1 promoted the proliferation and metastasis of glioma by regulating miR-1207-3p/HNF1B/MAPK pathway." (PMID 34475987, 2021). "HNF1β was a direct target of miR-217, and played oncogenic role in glioma cells." (PMID 28219405, 2017). "Moreover, glioma cells treated with miR-217+HNF1β (non-3′UTR) showed a lower apoptosis ratio than cells treated with miR-217+HNF1β." (PMID 28219405, 2017). "To clarify whether HNF1β reversed miR-217-induced impairment of malignant progression of glioma cells, we measured the biological behavior of glioma cells that stably expressed miR-217+HNF1β (non-3′UTR)." (PMID 28219405, 2017). "More importantly, inhibition of circ-TTBK2/miR-217/HNF1β/Derlin-1 axis may be a potential therapeutic target for human gliomas." (PMID 28219405, 2017). "We next aimed to investigate whether HNF1β was involved in the circ-TTBK2-mediated regulation of glioma cell progression." (PMID 28219405, 2017). "Since Derlin-1 could be upregulated by HNF1β, we first examined the expression and function of Derlin-1 in glioma tissues and cells." (PMID 28219405, 2017). "In addition, Derlin-1, identified as an oncogene in glioma tissues and cells, was involved in the HNF1β-mediated promotion of glioma cells malignant progression." (PMID 28219405, 2017). "Furthermore, protein levels of HNF1β were significantly higher in low- and high-grade glioma tissues than those in normal brain tissues." (PMID 28219405, 2017).
glioma (continued). "Moreover, qRT-PCR and western blot were used to determine the expressions of HNF1β mRNA and protein in glioma cells treated with circ-TTBK2 inhibition and/or miR-217 overexpression." (PMID 28219405, 2017). "Therefore, we suggested that lncRNA-PVT1/miR-1207-3p/HNF1B axis might play critical roles in glioma progression, indicating that lncRNA-PVT1/miR-1207-3p/HNF1B signaling axis may serve as novel molecular targets for glioma prevention and treatment." (PMID 34475987, 2021). "Furthermore, we showed that the anti-metastatic roles of lncRNA-PVT1 inhibition on glioma cells invasion could be abolished by co-transfected with miR-1207-3p inhibitors (or pcDNA3.1_HNF1B plasmid)." (PMID 34475987, 2021). "Flow cytometry analysis was used to measure whether HNF1β affected the apoptosis of glioma cells." (PMID 28219405, 2017). "However, the potential oncogenic function of HNF1β in glioma remains poorly defined." (PMID 28219405, 2017). "Given that Derlin-1 could be activated by HNF1β, and miR-217 modulated glioma cell progression via targeting 3′-UTR of HNF1β, we next sought to investigate whether Derlin-1 and the downstream pathways were involved in miR-217-induced blunting effect on glioma cells." (PMID 28219405, 2017). "Also, our data showed that HNF1β served as an oncogene in glioma cells." (PMID 28219405, 2017). "Circ-TTBK2 regulated the miR-217/HNF1b/Derlin-1 pathway to promote the progression of glioma; and circ-SHKBP1 regulated the angiogenesis of U87 glioma-exposed endothelial cells through miR-544a/FOXP1 and miR-379/FOXP2 pathways." (PMID 31179240, 2019). "To determine whether the effects of lncRNA-PVT1 in glioma cells metastasis were dependent on miR-1207-3p/HNF1B axis, we further tested the roles of lncRNA-PVT1/miR-1207-3p/HNF1B axis in glioma progression." (PMID 34475987, 2021). "First, we found that overexpression of HNF1β (without 3′-UTR) reversed inhibition on glioma cell malignant biological behavior induced by miR-217." (PMID 28219405, 2017). "Then, our results demonstrated that Derlin-1, p-PI3K, p-AKT, p-ERK, and p-MEK1/2 were distinctly restored when glioma cells were co-transfected with miR-217 and HNF1β (without 3′-UTR)." (PMID 28219405, 2017). "Moreover, HNF1β was a direct target of miR-217 and activated Derlin-1 via binding to its promoter via PI3K/AKT and ERK signaling pathways, suggesting blockage of circ-TTBK2/miR-217/HNF1β/Derlin-1 axis may be a potential therapeutic target for human gliomas." (PMID 32061256, 2020).
Hepatic cysts (5 papers, 2018 to 2025). "Two with HNF1B mutations had no combined hepatic cysts, and their kidney functions were within the normal range." (PMID 31056860, 2019). "Patients with HNF1B-MODY often have additional extra-pancreatic features, such as renal and/or hepatic cysts, elevated liver enzymes, genitourinary malformations, mental retardation, or eye defects." (PMID 36294752, 2022).
Intellectual disability (5 papers, 2020 to 2025). "In other studies, a few patients with intellectual disabilities and intragenic HNF1B mutations have been mentioned." (PMID 32708349, 2020). "Furthermore, there is evidence to suggest that HNF1B mutations are associated with an increased risk of certain neurodevelopmental disorders, including autism spectrum disorder, intellectual disability, and learning disabilities." (PMID 37511676, 2023).
kidney cancer (5 papers, 2010 to 2023). Primary or metastatic malignant neoplasm involving the kidney. "HNF1β, a candidate pRCC master TF, has been shown to be expressed in the embryonic kidney and in pRCC, and it is upregulated in pRCC compared to other kidney cancer histologies." (PMID 36681680, 2023). "Interestingly, HNF1B and PAX8 were both highly expressed and sufficient to impact proliferation/survival of kidney cancer cell lines, making them prime candidates for downstream analyses." (PMID 31431624, 2019).